HLA-F (major histocompatibility complex, class I, F)
Description:
Non-classical major histocompatibility class Ib molecule postulated to play a role in immune surveillance, immune tolerance and inflammation. Functions in two forms, as a heterotrimeric complex with B2M/beta-2 microglobulin and a peptide (peptide-bound HLA-F-B2M) and as an open conformer (OC) devoid of peptide and B2M (peptide-free OC). In complex with B2M, presents non-canonical self-peptides carrying post-translational modifications, particularly phosphorylated self-peptides. Peptide-bound HLA-F-B2M acts as a ligand for LILRB1 inhibitory receptor, a major player in maternal-fetal tolerance. Peptide-free OC acts as a ligand for KIR3DS1 and KIR3DL2 receptors. Upon interaction with activating KIR3DS1 receptor on NK cells, triggers NK cell degranulation and anti-viral cytokine production. Through interaction with KIR3DL2 receptor, inhibits NK and T cell effector functions. May interact with other MHC class I OCs to cross-present exogenous viral, tumor or minor histompatibility antigens to cytotoxic CD8+ T cells, triggering effector and memory responses. May play a role in inflammatory responses in the peripheral nervous system. Through interaction with KIR3DL2, may protect motor neurons from astrocyte-induced toxicity.
Synonyms: HLA-5.4; HLAF; CDA12; HLA-CDA12
Tractability: Antibody: UniProt places it where antibodies can reach, with high confidence; its Gene Ontology location is reachable by antibodies, with high confidence; UniProt predicts a signal peptide or a membrane-spanning region. PROTAC: ubiquitination databases record sites on it.
Gene: Protein-coding gene on chromosome 6 (29,722,738 to 29,738,528, forward strand). Ensembl gene ENSG00000204642.
Subcellular location: Cell membrane; Early endosome membrane; Lysosome membrane
Pathways (Reactome):
Immune System: Antigen Presentation: Folding, assembly and peptide loading of class I MHC; ER-Phagosome pathway; Endosomal/Vacuolar pathway; Immunoregulatory interactions between a Lymphoid and a non-Lymphoid cell; Interferon alpha/beta signaling; Interferon gamma signaling
Disease: SARS-CoV-2 activates/modulates innate and adaptive immune responses
Gene Ontology:
Molecular function: 14-3-3 protein binding; beta-2-microglobulin binding; peptide antigen binding; protein binding; TAP1 binding; TAP2 binding; signaling receptor binding
Biological process: antigen processing and presentation of endogenous peptide antigen via MHC class Ib; antigen processing and presentation of exogenous peptide antigen via MHC class Ib; negative regulation of natural killer cell cytokine production; negative regulation of natural killer cell degranulation; negative regulation of natural killer cell mediated cytotoxicity; negative regulation of T cell cytokine production; positive regulation of natural killer cell cytokine production; positive regulation of natural killer cell degranulation; positive regulation of T cell mediated cytotoxicity; antigen processing and presentation of endogenous peptide antigen via MHC class I via ER pathway, TAP-independent; immune response; regulation of natural killer cell mediated immunity
Cellular component: cell surface; early endosome membrane; endoplasmic reticulum; Golgi membrane; lysosomal membrane; membrane; MHC class Ib protein complex; plasma membrane; ER to Golgi transport vesicle membrane; external side of plasma membrane; lumenal side of endoplasmic reticulum membrane; phagocytic vesicle membrane; recycling endosome membrane
Genetic constraint (gnomAD): Loss-of-function variants: 48 observed, 50.44 expected, observed/expected ratio (o/e) 0.95, 90% interval 0.75 to 1.21. The upper end of that interval is the gene's LOEUF score, 1.21, which puts it in group 5 of 6, group 1 being the genes least tolerant of losing a copy. Missense variants: 496 observed, 588.84 expected, observed/expected ratio (o/e) 0.84, 90% interval 0.78 to 0.91. Synonymous variants: 203 observed, 234.99 expected, observed/expected ratio (o/e) 0.86, 90% interval 0.77 to 0.97.
Homologues: Orthologues: chimpanzee PATR-F (97% identical), macaque MAMU-F (73% identical), dog DLA-64 (52% identical), dog DLA-79 (50% identical), zebrafish si:ch211-147g22.4 (15% identical), zebrafish mhc1lia (12% identical). Paralogues in human: HLA-A (63% identical), HLA-B (63% identical), HLA-C (61% identical), HLA-G (60% identical), HLA-E (57% identical), HFE (28% identical), MR1 (28% identical), AZGP1 (23% identical), FCGRT (22% identical), MICB (22% identical), MICA (21% identical), CD1A (19% identical), and 10 more.
Diseases named in the same sentence as HLA-F in open-access papers:
HLA-F is named in the same sentence as 74 diseases in open-access papers, as found by Europe PMC text mining. Sharing a sentence is not in itself a finding about the gene and the disease. The quoted sentences say what the papers report.
breast carcinoma (14 papers, 2016 to 2024). "As previous studies revealed that an increased tumor lesion HLA-F expression has been associated with poor prognosis in patients with gliomas, nasopharyngeal carcinoma, stage II breast cancer, and esophageal squamous cell carcinoma." (PMID 31134067, 2019). "Accumulative clinical evidence has confirmed that HLA-F expression is associated with the clinical parameters and outcomes of several malignant tumours, such as breast cancer, gastric cancer, neuroblastoma, and hepatocellular carcinoma." (PMID 30510890, 2018). "The primary aim of the study was therefore to analyse the distribution of HLA-G and HLA-F across the molecular subgroups of breast cancer." (PMID 32978482, 2020). "HLA-E and HLA-F were also investigated in breast cancer and other solid tumors where it was observed that HLA-F expression positively correlated with tumor size and poor five-year survival rate." (PMID 32784928, 2020). "The aim of this study was to evaluate the prognostic and predictive value of HLA-G and HLA-F protein isoform expression patterns in patients with breast cancer." (PMID 32978482, 2020). "In summary, this study suggests that HLA-G and HLA-F may play an immunoregulatory role in breast cancer, on the basis of specific analysis of isoforms and splicing variants." (PMID 32978482, 2020). "Due to the different immunosuppressive effects of the HLA-G isoforms and the diverse role of HLA-F, these proteins could be of interest for the investigation of pathogenesis and progression and as a therapeutic target for breast cancer." (PMID 32978482, 2020). "For luminal B-like breast cancer samples, an overall low percentage (12–22%) of patients who achieved pCR was observed, independently of the expression of HLA-F and HLA-G isoforms, in comparison with the pCR rates in the HER2+ and triple-negative BC subcohorts (46–86% and 32–71%, respectively)." (PMID 32978482, 2020). "The findings of the present study may suggest that there is an impact of expression of HLA-F protein isoforms F1 and F3 and pCR in patients with luminal B-like breast cancer." (PMID 32978482, 2020). "For example, DENR and HLA-F were suggested as important players in breast cancer cells." (PMID 30911020, 2019). "Restoration of HPSE, HLA-F, or SELL expression in CDYL2b-overexpressing cells attenuated the ability of CDYL2b to suppress breast cancer cell migration and invasion." (PMID 32373210, 2020). "Transwell cell migration and invasion assays showed that overexpression of CDYL2b in MDA-MB-231 and Hs578T cells suppressed breast cancer migration and invasion, which was partially rescued by expressing HPSE, HLA-F, and SELL in these cells." (PMID 32373210, 2020). "In stage II breast cancer, overall survival of patients with HLA-F expression is lower than the one in those without HLA-F expression." (PMID 32373210, 2020). "To further verify that CDYL2b affects the migratory and invasive potential of breast cancer cells through transcriptional repression of HPSE, HLA-F, and SELL, we conducted rescue experiments by restoring HPSE, HLA-F, and SELL expression in MDA-MB-231 and Hs578T cells stably expressing CDYL2b." (PMID 32373210, 2020). "In the present study, however, correlation analyses between isoform-specific HLA-G and HLA-F expression and overall survival were not yet possible, as the study also included patients with recently diagnosed breast cancer." (PMID 32978482, 2020). "The HLA-F-positive group showed significantly poorer outcomes than the HLA-F-negative group in stage II breast cancer (p < 0.05)." (PMID 30510890, 2018). "Hence, CDYL2b might regulate the migration, invasion, and metastasis of breast cancer through, at least partly, regulating HPSE, HLA-F, and SELL expression." (PMID 32373210, 2020).
viral infection (10 papers, 2019 to 2025). "We can speculate that an overexpression of CST1 mimics a virus infection and causes therefore a downregulation of HLA‐F." (PMID 38270326, 2024). "Further in vitro experiments in airway epithelial cell infection models from healthy, asthma, and COPD revealed that IRF1 and HLA-F were rapidly activated within 24 h after viral infection in cells from healthy participants." (PMID 40420582, 2025). "Reviewing the emerging roles of HLA-F in immune modulation and viral infection, Lin and Yan categorized functional roles for different faces of HLA-F." (PMID 35214796, 2022). "More recently, HLA-F expression was found to be upregulated and to, perhaps, play an important role during the progression of viral infection." (PMID 31134067, 2019). "Not only the role of HLA-F in tumors, but also its regulation during viral infection seems to be highly ambiguous." (PMID 31717259, 2019). "In viral infection, HLA-F acts as a stress signal on virus-infected cells, which activates KIR3DS1+ NK cells, inhibiting viral replication and killing the infected cells." (PMID 31134067, 2019). "Since the functions of NK cells in COPD have remained unclear, the differentiated organotypic bronchoepithelia might serve as a simplified model to unravel the interaction of NK cells with HLA-F upon viral infection." (PMID 36713229, 2022). "Previous studies have revealed that HLA-F expression might be involved in various physiological and pathological processes, such as pregnancy, viral infection, cancer, transplantation, and autoimmune diseases." (PMID 31134067, 2019). "Thus far, it has been found that HLA-F regulates immunity during viral infection, pregnancy and autoimmunity through its interaction with certain KIR receptors." (PMID 31717259, 2019). "In the context of bacterial or viral infections, elevated levels of IFN-γ and NF-κB upregulate HLA-F expression, facilitating immune regulation." (PMID 40251569, 2025). "In the present review, we summarize the studies on the role of HLA-F in immune modulation, with a special emphasis placed on the roles of HLA-F and KIR3DS1 interactions in viral infection." (PMID 31134067, 2019). "Nonetheless, the role and importance of non-classical HLA class I molecules, particularly HLA-F and -G, in virus infections remains largely elusive." (PMID 41425562, 2025).
gastric cancer (9 papers, 2015 to 2024). A primary or metastatic malignant neoplasm involving the stomach. "In addition, clinical factors associated with gastric cancer are independently influenced by HLA-E and HLA-F." (PMID 36923953, 2023). "HLA-F has also been implicated in gastric cancer, along with another of its family, HLA-E45." (PMID 31267007, 2019). "We could not find the gene expression data for HLA-E and thyroid cancer with BRAF mutation in other studies, but HLA-E and HLA-F expression significantly correlated with depth of invasion, nodal involvement, lymphatic invasion, and venous invasion in gastric cancer patients." (PMID 36975440, 2023). "The expression of HLA-F closely correlates with nodal involvement, lymphatic invasion, venous invasion, and poor prognosis in patients with gastric cancer." (PMID 32373210, 2020). "Recent studies have demonstrated enhanced HLA-F expression in cancer stroma in the case of both breast and gastric cancers." (PMID 28210261, 2017).
glioma (9 papers, 2019 to 2025). A benign or malignant brain and spinal cord tumor that arises from glial cells (astrocytes, oligodendrocytes, ependymal cells). "HLA‐F membrane‐bound expression was also described on placental extravillous trophoblasts (reviewed in53) and has recently been linked to cell proliferation in glioma." (PMID 35988034, 2022). "Furthermore, HLA-F-positive gliomas were associated with immune response, indicating that the function of HLA-F in gliomas involved the regulation of immune status of tumor tissues." (PMID 30755240, 2019). "In a glioma cell line, HLA-F was found to promote cell proliferation in vitro by promoting HK2 protein stabilization and glycolysis." (PMID 40251569, 2025). "More specifically, it was reported that HLA-F promotes glioma cell proliferation via HK2-dependent glycolysis." (PMID 40251569, 2025). "In recent years, HLA-F has been found to play a role in a variety of cancers, including glioma (GM)." (PMID 33867844, 2021). "In gliomas, the expression of HLA-F also correlates with malignant phenotype and poor overall survival." (PMID 32373210, 2020). "Our study focused on the human leukocyte antigen (HLA) system that is responsible for regulating the immune system, and discovered the relationship between HLA-F expression and clinical prognosis in gliomas." (PMID 30755240, 2019). "In conclusion, to the best of our knowledge, this was the first study to investigate the HLA-F expression levels in gliomas." (PMID 30755240, 2019). "HLA-F was negatively correlated with overall survival (OS) in all grades of glioma and glioblastoma (GBM)." (PMID 30755240, 2019). "Our findings indicated that HLA-F significantly predicted the OS in all grade gliomas and GBM." (PMID 30755240, 2019). "We hypothesiz that HLA-F plays as an oncogene in glioma and is suggested as a new potential biotarget for therapy." (PMID 30755240, 2019). "Higher HLA-F expression in glioma cell surface provided immunoinhibitory effects and protected malignant glioma cells from elimination by NK cells, inducing the growth of glioma cells." (PMID 30755240, 2019). "In our opinion, during the development of gliomas, glioma-specific and microenvironment cue-induced HLA-F expression could be modulated on glioma cells." (PMID 30755240, 2019). "HLA-F expression was positively correlated with malignant phenotype and negatively correlated with OS, indicating that HLA-F could predict the immune state of gliomas and might be a clinical target of glioma immunotherapy." (PMID 30755240, 2019). "The results demonstrated that HLA-F could be considered as a novel immunotherapy target in gliomas." (PMID 30755240, 2019). "Furthermore, expression of HLA-F is associated with a negative overall survival in non-small cell lung cancer and gliomas." (PMID 31717259, 2019). "The results of univariate regression showed that HLA-F (p < 0.001) along with grade (p < 0.0001), age (p < 0.0001), and IDH1 status (p < 0.0001) predicted the OS in all grade gliomas." (PMID 30755240, 2019). "Then, we evaluated the survival time of each group and found that the patients with higher HLA-F expression have remarkably shorter OS in all grade gliomas and GBM in the CGGA RNA-seq set (p < 0.0001 for all grade gliomas, p = 0.0587 for GBM)." (PMID 30755240, 2019). "Lack of HLA-F could render gliomas to be susceptible to elimination by NK cells." (PMID 30755240, 2019).
hepatocellular carcinoma (6 papers, 2015 to 2024). A malignant tumor that arises from hepatocytes. "These researchers found that HCV infection can significantly upregulate cell surface HLA-F expression on the hepatoma cell line Huh7.5, which lacks intrinsic HLA-F expression." (PMID 31134067, 2019). "In hepatocellular carcinoma, HLA-F expression was significantly correlated with the degree of lymphatic or venous invasion." (PMID 30755240, 2019).
autoimmune disease (5 papers, 2019 to 2026). A disorder resulting from loss of function or tissue destruction of an organ or multiple organs, arising from humoral or cellular immune responses of the individual to their own tissue constituents. "While HLA-F polymorphism has been associated with autoimmune diseases, including multiple sclerosis and rheumatoid arthritis, they have not yet been linked to type 1 diabetes (GWAS Catalogue: accessed on Mar 21, 2024)." (PMID 41462339, 2025). "Higher expression of HLA-F and its genetic variants has been related to a predisposition to autoimmune diseases, such as SLE, rheumatoid arthritis and ankylosing spondylitis." (PMID 37153570, 2023). "For example, the genetic variants and protein expression of HLA-F have been observed to be associated with different types of diseases, such as cancer, infection, reproduction, and autoimmune disorders." (PMID 31134067, 2019). "Taken together, these findings show that PSMB9, CD74, and HLA-F all play important roles in presenting antigens and triggering autoimmune diseases." (PMID 37153570, 2023). "The exact function of HLA‐F remains unknown, but recent publications emphasise the essential immunological role of this gene in infectious diseases, cancer research, organ transplantation and autoimmune diseases." (PMID 41537416, 2026).
COVID-19 (5 papers, 2021 to 2025). A disease caused by infection with severe acute respiratory syndrome coronavirus 2. "From the analysis of the two cohorts, HLA-B, -C, -DRB1 and -DRB5 were significantly associated with COVID-19 severity, whereas HLA-F and -DQB1 lost significance." (PMID 39684907, 2024). "In our population, HLA-F is among the least variable genes; a single variant, having an allelic frequency of 0.04 in the global population and 0.06 in female cases, confers a 5-fold increased risk of severe COVID-19." (PMID 39684907, 2024). "Furthermore, we found that the genes mediated by high levels of estrogen highly overlapped with the risk genes for COVID-19 and asthma diseases, involving HLA-DRA, HLA-F, and HLA-DOB." (PMID 39872660, 2024). "Interestingly, we also noticed that estrogen-induced the expression of many of the COVID-19 and asthma-related risk genes involving HLA-DRA, HLA-F, and HLA-DOB, which play an important role in the immune response." (PMID 39872660, 2024). "Protein-protein interaction analysis of the effects exerted by anti-COVID-19 vaccination revealed one cluster comprised mainly of various HLA types, i.e., HLA-DOB, HLA-F, HLA-G, and ISG20." (PMID 39744634, 2024). "In CMs, HLA-F was specifically upregulated across Non-COVID-19, Post-COVID-19 and Post-Vaccination conditions." (PMID 39994453, 2025).
esophageal squamous cell carcinoma (5 papers, 2015 to 2024). Esophageal squamous cell carcinoma (ESCC) is a type of esophageal carcinoma (EC) that can affect any part of the esophagus, but is usually located in the upper or middle third. "In esophageal squamous cell carcinoma, the expression of HLA-F was significantly correlated with the poor survival in patients." (PMID 34795689, 2021). "Furthermore, in esophageal squamous cell carcinoma, higher HLA-F expression indicated worse survival." (PMID 30755240, 2019). "In esophageal squamous cell carcinoma (ESCC) patients, positive HLA-F expression was observed not only in tumor lesions (58.1%) but also in the corresponding adjacent normal esophageal tissues (54.8%)." (PMID 25435979, 2015).
glioblastoma (5 papers, 2019 to 2024). The most malignant astrocytic tumor (WHO grade IV). "HLA-F mRNA is overexpressed in glioblastoma compared to healthy tissue; however, to date, there is no known link between HLA-F and EOC." (PMID 38067396, 2023).